EGFR (epidermal growth factor receptor)
Diseases named in the same sentence as EGFR in open-access papers (continued):
Sharing a sentence is not in itself a finding about the gene and the disease.
tumor (continued). "Three different RTKs—epidermal growth factor receptor (EGFR), mesenchymal-to-epithelial transition (MET) and platelet-derived growth factor receptor alpha (PDGFRα)—demonstrate highly variable gene expression in individual tumor cells." (PMID 33919246, 2021). "Currently, anti-VEGF, rather than anti-EGFR, agents are usually recommended as first-line and subsequent therapy for patients with right-sided primary tumours." (PMID 33928486, 2021). "In human tumor xenograft models expressing or overexpressing HER family members, allitinib showed antitumor activity, especially in those with HER2 overexpression or EGFR T790M mutant tumors." (PMID 34885957, 2021). "ERRFI1 expression was specifically and strongly (16-fold) upregulated in the LMS4/F2T2↑ tumor, explaining the downregulation of EGFR in this tumor in the absence of significant mRNA expression change." (PMID 33853673, 2021). "All groups except for MGMT unmethylated, EGFR not amplified group had significantly lower PCr/Pi ratio in tumor voxels compared to contralateral voxels (p < 0.0001)." (PMID 34298788, 2021). "In the present study, EGFR amplification was defined as different from EGFR gain, so + EGFR/− PTEN tumours never showed EGFR amplification." (PMID 34257410, 2021). "Targeted agents have been investigated for GC treatment, such as: HER-2, EGFR, VEGF/VEGFR, PI3K/mTOR, PARP, MMPs inhibitors and agents that could induce tumor cell apoptosis." (PMID 34770912, 2021). "In addition, we proved the efficacy of HSF1 inhibitors to induce apoptosis of several EGFR-TKI-resistant cell lines in vitro and to inhibit the tumor growth of PC9-ErlR cells in vivo." (PMID 34203709, 2021). "The findings reveal heterogeneous, tumor cell-intrinsic, EGFR/ERBB inhibitor-induced IFN pathway activation in HNSCC and suggest that individual tumor responses to oncogene-targeted agents are a sum of direct growth inhibitory effects and variably-induced participation of host immune cells." (PMID 33485341, 2021). "TargomiRs is a tumor suppressor comprising miR-16 mimic packaged in nonliving bacteria minicells with anti-EGFR bispecific antibody labelling." (PMID 34522211, 2021). "The novel anti-EGFR/VEGFR2 BsAbwas produced and purified using an Exp293 mammalian expression system and its anti-tumor effects were studied across different TNBC cell lines and tumor xenograft model." (PMID 33804477, 2021). "Meanwhile, as an EGFR activator, TMEM16A is considered as an oncogene or a tumor-promoting factor." (PMID 33681289, 2021). "These EGFR transduced signals promote GBM cell proliferation and invasion, and tumour progression." (PMID 34831480, 2021). "Tumor EGFR copy number did not turn out as a predictive biomarker for the efficacy of cetuximab plus platinum/5-FU as first-line therapy for patients with R/M HNSCC." (PMID 34307351, 2021). "For 26 patients (19.0%), the liquid biopsy test was performed without knowledge of the EGFR status in the tumor tissue." (PMID 34680416, 2021). "One of them studied an EGFR-directed CAR-T cell with inducible production and the release of transgenic IL-12 cytokine (NCT03542799), which is capable of modulating the tumour microenvironment and attracting and activating innate immune cells to attack the tumour." (PMID 34769211, 2021). "FAM188B knockdown reduced the levels of tumor proteins such as EGFR and FOXM1, suggesting that FAM188B may be a potential target controlling tumor malignancies." (PMID 33440835, 2021). "This test can detect specific EGFR mutations in the blood of NSCLC patients, who would not be able to provide a tumor biopsy for conventional EGFR testing due to advanced tumor stage, comorbidities, or tissue inadequacy." (PMID 34680433, 2021). "EGFR is an important therapeutic target for therapy with anti-EGFR antibodies, however, interestingly, the expression of EGFR is not used for patient selection due to reports of response to cetuximab in mCRC patients with EGFR negative tumours." (PMID 33562755, 2021).
tumor (continued). "The overall survival time for patients with EGFR‐amplified tumours exhibiting increased levels of phosphorylated JAK1 was significantly shortened compared with patients with tumours negative for one or both features." (PMID 33523587, 2021). "Of these six EGFR positive primary tumours, the corresponding metastatic sites were EGFR negative, whereas in four EGFR positive metastasis, the primary tumours were EGFR negative." (PMID 33562755, 2021). "BiTEs are fusion proteins consisting of two scFv fragments; one specific for surface markers ubiquitously expressed on effector cells—CD3 for example—and the other specific for antigens highly expressed on the tumour, such as mesothelin, the disialoganglioside GD2, or EGFR." (PMID 34885108, 2021). "The TLR4 activation, the receptor for LPS generated by the gut microbiome in the epithelial cells, can induce tumor development by up-regulating prostaglandin-endoperoxide synthase 2 (PTGS2) and activating the epidermal growth factor receptor (EGFR) signaling pathway in mice receiving AOM." (PMID 34556055, 2021). "Notably, the patient (P2) who received multiple EGFR TKIs likely acquired FGFR3 R248C and/or G380R to overcome the anti-tumor activity of TKIs, including osimertinib and afatinib, although pretreatment samples were unfortunately not available." (PMID 33710807, 2021). "Moreover, based on other previous literature reports, EGFR is located upstream of the ERK signaling pathway, which activates ERK signaling pathway in tumor to promote tumor development." (PMID 33407520, 2021). "The combination effect was EGFR-mediated, since the non-tumor (tetanus toxoid)-targeted ADC had little or no synergistic effect with navitoclax." (PMID 34207383, 2021). "This phenomenon implied that the tumor evolutionary trajectories may had some difference between EGFR wild-type SCC and EGFR-mutant SCC." (PMID 34195081, 2021). "The activity of EGFR, PI3K, and 12 other key oncogenic pathways was inferred by the PROGENy algorithm from the normalized RNA-seq data of the TCGA-HNSC cohort consisting of 498 tumor samples." (PMID 34178665, 2021). "EGF-stimulated EGFR phosphorylation induces the S100A2 expression, and S100A2 exhibits antitumor activity by reducing the rate of tumor growth when overexpressed in nude mice with NCI-H2172 cell tumor xenograft model." (PMID 34239729, 2021). "Furthermore, PD-L1 expression can be up-regulated in tumor cells that are resistant to chemotherapeutic agents, including tumor-targeting drugs such as EGFR-TKI, thus promoting immune escape of tumor cells." (PMID 35002732, 2021). "Most importantly, all seven bsAbs that were scrutinized more meticulously in terms of killing abilities elicited robust NK cell mediated lysis of tumor cells in a targeted fashion with negligible killing of EGFR-negative cells." (PMID 35087526, 2021). "Current evidence indicates that decorin plays role in tumor cell cycle arrest and cell apoptosis through epidermal growth factor receptor (EGFR) pathway, and decorin also inhibits tumor angiogenesis after formation of a heterodimeric complex with its key receptor Met." (PMID 34386415, 2021). "The KEYNOTE-001 study showed that in patients with PD-L1 overexpression (i.e., tumor proportional score [TPS] > 50%), pembrolizumab was less effective in EGFR-mutant tumors than in EGFR wild-type tumors (median overall survival = 6.5 vs. 15.7 months, respectively)." (PMID 34496872, 2021). "In 2019, the indication for pembrolizumab was expanded as the first‐line treatment for advanced NSCLC patients with PD‐L1 expression (Tumor Proportion Score [TPS] ≥1%) and no EGFR or ALK mutations." (PMID 34977873, 2021).
tumor (continued). "The levels of other T cell recruiting chemokines, MIP-1β and RANTES were higher in the supernatants from HER2- or EGFR hCART41BBζ, hCARTICOSζ and hCARTICOS-27ζ, COATC and BATs co-cultured with tumor targets at 1:1 E:T ratio compared to their corresponding unarmed hCART, COATC and ATC." (PMID 34290709, 2021). "Furthermore, phosphorylation status of EGFR at Y1068 and Y1173 along with the downstream mediator STAT3 (Y705) was shown to decrease in tumor tissue in Anthos treated mice." (PMID 34926717, 2021). "As expected, when NK cells (either resting or activated) were co-cultured with the EGFR− Colo829 tumor cell line, no NK cell degranulation nor tumor cell cytotoxicity was induced by the bispecific VHHs (p > 0.05)." (PMID 34771609, 2021). "Although currently not considered for GBM tumor subtyping, in 50% of cases with EGFR amplifications, tumors also carry a truncated form of EGFR that possesses constitutive kinase activity, which is named EGFRvIII, or otherwise EGFR type III, de2–7, ΔEGFR)." (PMID 34830952, 2021). "We wondered if AXL-positive cells are present in tumors before treatment as well as in tumor-derived cell lines and whether these cells bear phenotypic and molecular similarities to the AXL-positive cells that are generated upon exposure to EGFR TKi." (PMID 34254585, 2021). "The following assays were conducted on SCC4 or SAS tumors for the EGFR marker: Ki67 marker was used for cell proliferation staining; CD31 marker was used for microvessel formation; cleaved caspase-3 was used to mark tumor cell apoptosis and TUNEL was used to stain DNA fragmentation." (PMID 34575510, 2021). "Primary resistance corresponds to a rare situation of intrinsic or innate resistance before any EGFR-TKIs administration, with early tumor progression without prior tumor response." (PMID 34638411, 2021). "EGFR-amplified cells are preferentially located at the infiltrating edge rather than distributed uniformly within GBM tumors 54, thus more likely to provide the higher contrast in order to delineate the tumor tissue from normal brain." (PMID 34158840, 2021). "LAT005, a patient in the third cohort, who underwent unilateral adrenalectomy as a method of LAT, had a decreased tumor burden due to the surgery; however, this was not mirrored by a decrease in mutant EGFR AF." (PMID 34283064, 2021). "First, we did not use NSCLC cell lines with EGFR L858R mutation, although we showed that ZEB1 was highly expressed in tumor specimens from NSCLC patients with EGFR L858R mutation after gefitinib resistance." (PMID 33764690, 2021). "Anti-EGFR/VEGFR2 BsAb demonstrates in vitro and in vivo anti-tumor activity in TNBC models." (PMID 33804477, 2021). "The inhibition of the mTOR signaling pathway in tumors by zotarolimus reduced CD44, EGFR, TGF-β, and VEGF expression, which could decelerate the migration and invasion of tumor cells in cancer metastasis." (PMID 34361836, 2021). "Among 67 tumor specimens from GBC patients, all were positive for EGFR even though EGFR is expressed mainly in the plasma membrane, 16% (11 cases) of EGFR-positive tumor specimens showed cytoplasmic EGFR expression." (PMID 32989241, 2021). "Myeloid cells also appear to support immune evasion in PDAC through EGFR/MAPK-dependent regulation of PD-L1 expression on tumor cells, since depletion of myeloid cells prevented KrasG12D-driven PDAC initiation and restored CD8+ T cell anti-tumor immunity." (PMID 34572737, 2021). "One obstacle is the choice of an appropriate target, as most conventional solid tumor antigens such as EpCAM, HER2 or EGFR are not tumor-specific, being expressed to various degrees in healthy tissues as well." (PMID 34484225, 2021). "We were unable to compare the EGFR status of cerebrospinal fluid samples and intracranial tumors due to the absence of intracranial metastatic tumor tissue." (PMID 33828979, 2021).
tumor (continued). "Finally, the combination of anti-EGFR and anti-VEGF therapy shows better tumor inhibition than single anti-VEGF therapy, which is beneficial to optimize the clinical treatment of NPC." (PMID 33875643, 2021). "Constitutive expression of PD-L1 by tumor cells is frequently due to active oncoproteins, such as MYC, EML4-ALK, and AKT, but how oncogenic forms of the epidermal growth factor receptor (EGFR) regulate the expression of PD-L1 is still incompletely understood." (PMID 34038737, 2021). "Besides, EGFR (epidermal growth factor receptor) and integrinβ can integrate with IGFBP2 to promote tumor progression." (PMID 34394352, 2021). "In this study, the co-expression of CXCR5 in CAR-T was designed to not only increase the infiltration of CAR-T cells but also to mitigate potential off-tumor toxicity, due to our results that CAR-T only infiltrates into EGFR and CXCL13 double-positive tumor sites and produces a killing effect." (PMID 34553036, 2021). "Although VM inhibition was seen in vitro with Fc-E-P125A, which does not target EGFR, αEGFR-E-P125A demonstrated greater efficacy against EGFR+ MDA-MB-468 xenografts than Fc-E-P125A in vivo, suggesting that EGFR targeting is needed for optimal anti-tumor efficacy." (PMID 34831127, 2021). "The binding of this BsAb to CD3 and EGFR was strongly reduced in vitro in the absence of proteases, whereas in vivo anti-tumor efficacy was retained." (PMID 33466732, 2021). "Several lines of evidence suggest the use of novel therapy, such as CAPTEM, PRRT, EVE, immunotherapy, EGFR inhibitors, CDK2 inhibitors, and RA, could be valuable strategies for long-term tumor control." (PMID 33841328, 2021). "EGFR-induced mTOR can stimulate the expression of IL6 through the classic pathway and reprogram IL-6 nonresponsive cells into IL-6 responder cells, to further affect the sensitivity of the tumor cells to IL-6." (PMID 33582655, 2021). "Researchers compared the binding ability of TR-PIN to tumor cells with different levels of receptor expression (EGFR, TfR or HER-2), and found that TR-PIN has the ability to recognize multiple tumor targets, effectively photodynamically eradicating different tumor subsets and reducing escape." (PMID 34834367, 2021). "The regularity of TVC after EGFR-TKI treatment is that the volume shrinkage gradually slows the volume continues to shrink after increasing in some cases, and tumour shrinkage varies due to the different sensitivities of EGFR-TKI treatment in different patients." (PMID 34631535, 2021). "Theoretically, the tumor environment is different in osimertinib-naive and pre-treated patients, and excessive inhibition of VEGF may affect the efficacy of EGFR-TKI." (PMID 35046801, 2021). "To confirm whether the GR–MIG6 axis modulates EGFR expression in human HCC, we performed GR and EGFR immunohistochemical staining in human HCC tissues and their corresponding non-tumor liver tissues." (PMID 33806040, 2021). "Then, the RNA expression of genes from the EGFR signaling axis (KRAS, NRAS, BRAF, EGFR, and MET), a tumor stem cell marker (PROM1), EGFR-resistance genes (TRAP1, AXL, PRSS1, and EPHA2) and EGFR-sensitive genes (ERBB3, ERBB2, EREG, AREG, NT5E, and PTEN) were mapped across the pseudotime trajectory." (PMID 34745987, 2021). "However, inhibition of EGFR-signaling via cetuximab is known to interrupt INF-γ signaling and prevent PD-L1 upregulation on tumor cells." (PMID 34557197, 2021). "As shown in a representative manner for patient #6, PD-L1, EGFR and EpCAM were expressed to a lower degree or on subsets of tumor cells while FAP expression was absent." (PMID 34484225, 2021).
tumor (continued). "Hedgehog signaling provided tumor cells with an escape mechanism from anti-EGFR treatment, which is dependent on EMT induction but not on EGFR signaling." (PMID 34771518, 2021). "Additionally, miR-7-5p has been reported to regulate the epidermal growth factor receptor (EGFR) and EGFR/phosphatidylinositol 3-kinase/protein kinase B/mechanistic target of rapamycin (PI3K/Akt/mTOR) signaling pathway to affect tumor cell growth." (PMID 33768139, 2021). "The development of trivalent CAR-Ts specific to IL13Rα2, the human epidermal growth factor receptor (HER-2) and EGFRvIII, was made possible by analysing interpatient variability of multiple GBM samples, showing tumor cell-specific cytotoxicity and tumor remission in vitro and in vivo models." (PMID 34557553, 2021). "ILT4 in EGFR-activated NSCLC cells induced TAM recruitment and M2-like polarization, inhibited T cell infiltration and cytotoxicity, and consequently created an immunosuppressive and tumor-promoting TME." (PMID 33537094, 2021). "EGFR-targeting fluorescent probes have demonstrated improved accuracy over 5-ALA in EGFR-positive tumours but not in wildtype tumours." (PMID 34298721, 2021). "Up to one-third of all GBMs harbor the epidermal growth factor receptor (EGFR) vIII mutation resulting in a constitutively active EGFR that does not bind its ligand, but rather, promotes tumor proliferation through downstream events." (PMID 33925295, 2021). "Although PDGFRA amplification is not as common as EGFR amplification, it is found in 11% of GBMs, making it the second most common tyrosine kinase receptor gene amplification in this tumor family." (PMID 34248623, 2021). "Anti-VEGF and EGFR antibodies could not only reduce CRC cells proliferation and invasion in vitro, but also inhibit the tumor growth and angiogenesis in vivo through inhibiting the activation of AKT and ERK signaling pathways." (PMID 34109130, 2021). "The efficacy of anti-EGFR therapy was shown to be restricted to the subgroup of patients with RAS or BRAFV600E wildtype tumours, as no benefit was observed in patients with tumours that harbour these mutations." (PMID 34253874, 2021). "We did not found expression of the EGFR vIII in grades I and II tumor as shown in S3 Fig in S1 Raw images." (PMID 34582442, 2021). "Moreover, studies have shown that, under pathological conditions, epidermal growth factor receptor (EGFR) is the driving force of tumorigenesis, and it is considered as a biomarker of tumor drug resistance." (PMID 34804186, 2021). "Additional tests revealed that epidermal growth factor receptor and anaplastic lymphoma kinase were negative, and the programmed death ligand 1 (PD-L1) expression rate in tumor cells was 40% (22C3 clones)." (PMID 34817132, 2021). "Importantly, this double-attack strategy can be adapted for use with any kind of therapeutic antibodies to target different tumor antigens (e.g., CD19, EGFR, HER2, etc.)to become second generation antibody drugs." (PMID 33422061, 2021). "The addition of stromal cells increased transcription of matrix remodelling proteins FN1 and MMP9, induced release of tumour-promoting immune molecules MIF, Serpin E1, CXCL1, IL-8 and CXCL12 and altered cancer cell expression of immunotherapeutic targets EGFR, CD47 and PD-L1." (PMID 34885111, 2021). "Also, in the model P8X26, the expression of 8 markers (i.e., Ki67, P63, GATA3, KRT5/6, KRT20, 34βE12, EGFR, and HER2) was similar between the original tumor and different generations." (PMID 35432811, 2021). "These EGFR‐targeting CAR NK cells were directly injected into the tumor in both a cell line‐derived and a patient's tumor‐derived breast cancer mouse model, and they were able to better control tumor growth than in controls." (PMID 33959279, 2021). "All other available covariates, including age and EGFR membrane expression in tumor cells, did not correlate with changes in inter patient variability and were excluded from the pharmacokinetic model." (PMID 34213592, 2021).